TSPAN11 (tetraspanin 11)
Description:
Facilitates focal adhesion assembly to regulate osteoblast alignment and guide bone matrix formation orthogonally to cell orientation.
Synonyms: VSSW1971
Tractability: Antibody: UniProt predicts a signal peptide or a membrane-spanning region; its Gene Ontology location is reachable by antibodies, with medium confidence.
Gene: Protein-coding gene on chromosome 12 (30,926,428 to 30,996,602, forward strand). Ensembl gene ENSG00000110900.
Subcellular location: Membrane
Subcellular location (Human Protein Atlas): Vesicles
Gene Ontology:
Biological process: focal adhesion assembly
Cellular component: plasma membrane; membrane
Genetic constraint (gnomAD): Loss-of-function variants: 26 observed, 32.29 expected, observed/expected ratio (o/e) 0.81, 90% interval 0.59 to 1.12. The upper end of that interval is the gene's LOEUF score, 1.12, which puts it in group 4 of 6, group 1 being the genes least tolerant of losing a copy. Missense variants: 278 observed, 330.94 expected, observed/expected ratio (o/e) 0.84, 90% interval 0.76 to 0.93. Synonymous variants: 140 observed, 144.39 expected, observed/expected ratio (o/e) 0.97, 90% interval 0.84 to 1.12.
Homologues: Orthologues: chimpanzee TSPAN11 (98% identical), macaque TSPAN11 (96% identical), pig TSPAN11 (88% identical), mouse Tspan11 (87% identical), rat Tspan11 (87% identical), guinea pig TSPAN11 (87% identical), rabbit TSPAN11 (86% identical), dog TSPAN11 (81% identical), zebrafish tspan11 (70% identical). Paralogues in human: CD151 (56% identical), TSPAN18 (30% identical), TSPAN9 (30% identical), TSPAN4 (29% identical), TSPAN5 (29% identical), TSPAN17 (28% identical), CD82 (28% identical), TSPAN1 (27% identical), TSPAN14 (27% identical), TSPAN33 (27% identical), TSPAN7 (27% identical), CD37 (26% identical), and 20 more.
Diseases named in the same sentence as TSPAN11 in open-access papers:
TSPAN11 is named in the same sentence as 15 diseases in open-access papers, as found by Europe PMC text mining. Sharing a sentence is not in itself a finding about the gene and the disease. The quoted sentences say what the papers report.
breast cancer (2 papers, 2019 to 2022). A primary or metastatic malignant neoplasm involving the breast. "To further validate the identified target genes that showed significant changes in DE and DM patterns in response to maternal BSp treatment, we evaluated gene expression of Avpr2, Cyp4a12b, Dpp6, Gria2, Pcdh9 and Tspan11 genes in the offspring mammary tumors using qRT-PCR." (PMID 35263365, 2022). "Analyses of the expression levels of all 33 tetraspanins revealed significantly higher expression of TSPAN1, TSPAN15, TSPAN8, TSPAN11, TSPAN29, and TSPAN27 in the breast cancer spheres than in non-CSCs." (PMID 31253779, 2019).
colon adenocarcinoma (1 paper, 2022). "An investigation in colon adenocarcinoma revealed that down-regulation of Tspan11 gene was positively correlated with infiltration of CD4+ T cells, macrophages, neutrophils and dendritic cells." (PMID 35263365, 2022).
colon cancer (1 paper, 2021). "The box plots suggested that the ITLN1, TSPAN11, CPRC5B, and CXCL13 genes were significantly lowly expressed in the colon cancer samples and the TIMP1 gene was highly expressed in the colon cancer samples in the TCGA cohort." (PMID 33579281, 2021). "In this study, we constructed a 6-gene signature (ITLN1, HOXD9, TSPAN11, GPRC5B, TIMP1 and CXCL13) prognostic stratification system based on the colon cancer invasion-related genes, and evaluated the stability and accuracy of the model." (PMID 33579281, 2021).
lung carcinoma (1 paper, 2023). "But TSPAN11, UPK1B, and UPK1A are currently not related to lung cancer research." (PMID 37516981, 2023).
periodontitis (1 paper, 2025). An acute or chronic inflammatory process that affects the tissues that surround and support the teeth. "MME and TSPAN11, two characteristic genes associated with PIGFs, may become targets for the treatment of periodontitis in the future." (PMID 40370461, 2025). "In conclusion, MME and TSPAN11 were closely associated with diverse immune cells, chemokine-related genes and HLA genes, suggesting their potential role in mediating immune responses in the pathogenesis of periodontitis." (PMID 40370461, 2025). "Additionally, we identified two genes (MME and TSPAN11) associated with this subpopulation that may be involved in the pathogenesis of periodontitis by promoting immune cell recruitment and exacerbating the immune response." (PMID 40370461, 2025). "Notably, MME and TSPAN11 were identified as key genes associated with this specific GFs subpopulation that may drive disease progression by exacerbating the inflammatory response, suggesting their potential as therapeutic targets for periodontitis." (PMID 40370461, 2025). "Collectively, these results strongly suggest that MME and TSPAN11 play critical roles in regulating GFs’ inflammatory responses and cellular behaviors, highlighting their potential as therapeutic targets for periodontitis." (PMID 40370461, 2025). "Differential gene analysis, WGCNA, and machine learning algorithms identified two genes (MME and TSPAN11) as potential therapeutic targets for periodontitis." (PMID 40370461, 2025). "LASSO regression and RF, two machine learning algorithms, were finally utilized to determine the two best signature genes (MME and TSPAN11) that are highly related with the onset or progression of periodontitis." (PMID 40370461, 2025). "The bioinformatics analysis in this study indicated that MME and TSPAN11 expression was upregulated in periodontitis samples." (PMID 40370461, 2025). "In conclusion, these findings suggest that GFs expressing MME and TSPAN11 may possess a strong ability to interact with immune cells, potentially exacerbating immune responses and promoting the development of periodontitis." (PMID 40370461, 2025).
tumor (4 papers, 2021 to 2024). "Tspan11 is a tumor mesenchymal-associated biomarker that correlates with tumor immunity." (PMID 38649381, 2024). "Tspan1, Tspan11, Tspan13, Tspan28, Tspan29, and Tspan30 have been identified as biomarkers for tumor diagnosis and prognosis, while Tspan8, Tspan24, and Tspan27 show potential as biomarkers." (PMID 38649381, 2024). "Studies have revealed that amongst the 6 identified target genes, Dpp6 and Pcdh9 were Tumor suppressor genes (TSGs) and Avpr2, Cyp4a12b, Dpp6, Gria2, Pcdh9 and Tspan11 were key tumor-related transcripts that can regulate various pathways during carcinogenesis." (PMID 35263365, 2022). "Tumor immune infiltration analysis results showed that TSPAN11, GPRC5B, TIMP1, and CXCL13 protein levels were significantly positively correlated with CD4+ T cells, macrophages, neutrophils, and dendritic cells." (PMID 33579281, 2021). "Pan-cancer expression analysis results showed that ITLN1, TSPAN11, CXCL13, and GPRC5B were downregulated and TIMP1 was upregulated in most tumor samples, including COAD, which was consistent with the results of the TCGA and GEO cohorts." (PMID 33579281, 2021).
cancer (3 papers, 2021 to 2024). A tumor composed of atypical neoplastic, often pleomorphic cells that invade other tissues. "A previous study has demonstrated that TSPAN11 was downregulated in pan-cancer and positively associated with CD4 + T cells, macrophages, neutrophils, and dendritic cells." (PMID 38167072, 2024). "TSPAN11 is one number of the Tetraspanins (TSPANs), which are a class of four transmembrane segmented proteins, TSPANs play dual roles in pan-cancer." (PMID 38167072, 2024). "Additional candidates are reported to be involved in cancer prognosis and progression, including TSPAN11, NKX6-1, and SLC16A1." (PMID 36975205, 2023). "We found that, compared with normal tissues, the TIMP1 protein was expressed highly and significantly in cancer samples, while the ITLN1, TSPAN11, CPRC5B, and CXCL13 proteins were expressed poorly in cancer samples." (PMID 33579281, 2021). "Compared with the expression levels in normal samples, ITLN1, TSPAN11, CPRC5B, and CXCL13 showed significantly low expression levels in most cancer types, including COAD, while TIMP1 was expressed highly in most cancer types." (PMID 33579281, 2021).
neurodevelopmental disorder (2 papers, 2023). A behavioral and cognitive disorder with onset during the developmental period that involves impaired or aberrant development of intellectual, motor, or social functions. "The results identified one potential KS candidate gene (TSPAN11), seven candidate genes for the neurodevelopmental disorder (TM7SF3, STK38L, ARNTL2, ERGIC2, TMTC1, DENND5B, and ETFBKMT), and four candidate genes for KS with ID (INTS13, REP15, PPFIBP1, and FAR2)." (PMID 37034680, 2023). "As a result, we identified a dozen candidate genes: TSPAN11 as a potential KS candidate gene, TM7SF3, STK38L, ARNTL2, ERGIC2, TMTC1, DENND5B, and ETFBKMT as candidate genes for the neurodevelopmental disorder, and INTS13, REP15, PPFIBP1, and FAR2 as candidate genes for KS with ID." (PMID 37563198, 2023).
infection (1 paper, 2025). The state of being infected such as from the introduction of a foreign agent such as serum, vaccine, antigenic substance or organism. "Additionally, genes related to cell adhesion such as ADGRF5, CAVIN2, FAT3, FILIP1, GSN, and TSPAN11 were downregulated in both the variants at 24hpi whereas CAV1, CAVIN1, GPC3, POSTN, SUSD2, and TSPAN7 were downregulated only after Delta variant infection at 24 hpi." (PMID 41200555, 2025).
TSPAN11 also shares sentences with these, for which no sentence is quoted: Alzheimer disease (1 paper); bipolar disorder (1); Obesity (1); schizophrenia (1); Stroke (1); uveal melanoma (1).